BAG2 (BAG cochaperone 2)
Description:
Co-chaperone for HSP70 and HSC70 chaperone proteins. Acts as a nucleotide-exchange factor (NEF) promoting the release of ADP from the HSP70 and HSC70 proteins thereby triggering client/substrate protein release.
Synonyms: BAG-2; dJ417I1.2
Tractability: PROTAC: ubiquitination databases record sites on it; its protein half-life has been measured.
Gene: Protein-coding gene on chromosome 6 (57,172,319 to 57,189,833, forward strand). Ensembl gene ENSG00000112208.
Subcellular location (Human Protein Atlas): Cytosol; Basal body; Centrosome; Mid piece; Principal piece
Pathways (Reactome):
Cellular responses to stimuli: Regulation of HSF1-mediated heat shock response
Disease: Dengue Virus Genome Translation and Replication
Gene Ontology:
Molecular function: adenyl-nucleotide exchange factor activity; identical protein binding; protein binding; protein-folding chaperone binding; transmembrane transporter binding; tau protein binding; heat shock protein binding; ubiquitin protein ligase binding
Biological process: negative regulation of protein ubiquitination; positive regulation of protein processing; protein metabolic process; protein stabilization; positive regulation of proteasomal protein catabolic process; positive regulation of proteasomal ubiquitin-dependent protein catabolic process; protein folding; positive regulation of protein metabolic process
Cellular component: protein folding chaperone complex; axon; cytosol; dendrite; dendritic microtubule; microtubule
Genetic constraint (gnomAD): Loss-of-function variants: 8 observed, 14.4 expected, observed/expected ratio (o/e) 0.56, 90% interval 0.32 to 1. The upper end of that interval is the gene's LOEUF score, 1, which puts it in group 4 of 6, group 1 being the genes least tolerant of losing a copy. Missense variants: 216 observed, 242.94 expected, observed/expected ratio (o/e) 0.89, 90% interval 0.8 to 1. Synonymous variants: 79 observed, 87.12 expected, observed/expected ratio (o/e) 0.91, 90% interval 0.75 to 1.09.
Homologues: Orthologues: chimpanzee BAG2 (100% identical), dog BAG2 (98% identical), pig BAG2 (96% identical), mouse Bag2 (93% identical), rat Bag2 (92% identical), guinea pig BAG2 (85% identical), tropical clawed frog bag2 (64% identical), zebrafish bag2 (63% identical), Caenorhabditis elegans unc-23 (36% identical), Drosophila melanogaster CG7945 (29% identical).
Diseases named in the same sentence as BAG2 in open-access papers:
BAG2 is named in the same sentence as 43 diseases in open-access papers, as found by Europe PMC text mining. Sharing a sentence is not in itself a finding about the gene and the disease. The quoted sentences say what the papers report.
breast carcinoma (10 papers, 2006 to 2025). "Bioinformatics analyses revealed that all six top canonical pathways, including the signallings of Actin cytoskeleton, ILK, VEGF, BAG2, Integrin, and Paxillin, are associated with the migration of breast cancer cells." (PMID 34571787, 2021). "These mechanistic studies support our results showing that high BAG2 expression is associated with frequent metastasis in patients with breast cancer." (PMID 34572878, 2021). "We investigated the prognostic value of BAG2-expression in cancer-associated fibroblasts (CAFs) and tumor cells in predicting metastasis-free survival in patients with breast cancer." (PMID 34572878, 2021). "We demonstrated that strong expression of BAG2 in either the tumor cells or CAFs is a significant risk factor for metastasis in patients with breast cancer." (PMID 34572878, 2021). "From this viewpoint, our finding is noteworthy that elevated BAG2 expression in the tumor stroma could be a risk factor for metastasis in patients with breast cancer." (PMID 34572878, 2021). "Evaluation of BAG2 expression on both CAFs and tumor cells could help in determining the risk of metastasis in breast cancer." (PMID 34572878, 2021). "Evaluation of BAG2 expression on both CAFs and tumor cells could lead to better evaluation of the risk of metastasis in patients with breast cancer." (PMID 34572878, 2021). "Evaluation of BAG2 expression on both CAFs and tumor cells could be helpful to estimate the risk of metastasis in breast cancer." (PMID 34572878, 2021). "Another pathway implicated in breast cancer discovered here was BAG2." (PMID 32545594, 2020). "Our findings suggest that evaluation of BAG2 expression in the tumor stroma in addition to within the tumor cells could contribute to finer stratification of the metastatic risk in patients with breast cancer." (PMID 34572878, 2021). "We then performed immunohistochemistry (IHC) to analyze BAG2 expression in a cohort of 236 patients with breast cancer who received chemotherapy." (PMID 36593950, 2023). "In the present study, we found that BAG2 was significantly upregulated in relapse breast cancer specimens and served as an independent predictor of poor prognosis in patients with breast cancer." (PMID 36593950, 2023). "The effects of BAG2 on the chemoresistance of breast cancer were demonstrated by cell function assays and mice tumor models." (PMID 36593950, 2023).
breast carcinoma (continued). "In the present study, we revealed that BAG2 was significantly upregulated in relapse breast cancer specimens and correlated with poor survival in patients with breast cancer." (PMID 36593950, 2023). "Here, we evaluated BAG2 expression of CAF and tumor cells and assessed metastasis risk in patients with breast cancer." (PMID 34572878, 2021). "Other studies also revealed that BAG2 supported proliferation and/or metastasis of tumors like breast cancer and oral cancer." (PMID 34257542, 2021). "Despite these limitations, our study clearly revealed differential metastatic events according to BAG2 expression in patients with breast cancer." (PMID 34572878, 2021). "Future study is warranted to address the relationship between CAF-related protein and BAG2 expression in breast cancer." (PMID 34572878, 2021). "Unlike BAG1, which has been widely studied as a favorable prognostic marker in breast cancer, the role of BAG2 in malignancies has been examined only in a few studies." (PMID 34572878, 2021). "Here, we evaluated the prognostic impact of BAG2 expression in CAF on the metastasis-free survival in breast cancer." (PMID 34572878, 2021). "Taken together, these results suggest that BAG2 may play a role in the progression of breast cancer with chemotherapy." (PMID 36593950, 2023). "We next explored the role of BAG2 in the chemoresistance of breast cancer." (PMID 36593950, 2023). "Additionally, our previous study revealed that BAG2 stimulates distant metastasis by promoting the secretion of pro-cathepsin B in breast cancer." (PMID 34572878, 2021). "Besides that, a high abundance of BAG2 regulates the pro-cathepsin B/annexin II complex formation and facilitates the secretion of pro-cathepsin B, which induce metastasis in breast cancer." (PMID 34571787, 2021). "Additionally, our results suggest the prognostic value of measuring BAG2 expression in CAF along with that in the tumor cells of breast cancer." (PMID 34572878, 2021). "Therefore, breast cancer cells with relatively low expression of BAG2 and LOXL1 may have a high possibility of resistance to IPI-504." (PMID 40426862, 2025). "However, the effect of BAG2 expression in CAF on the prognosis of breast cancer patients remains unknown." (PMID 34572878, 2021). "Interestingly, we previously noted that serum BAG2 levels were higher in patients with breast cancer than in healthy volunteers, suggesting that BAG2 in cancer patients could be secreted into blood." (PMID 34572878, 2021). "Thus, BAG2 may be a valuable target for preventing metastasis in patients with breast cancer." (PMID 34572878, 2021).
breast carcinoma (continued). "We co-treated breast cancer cells MDA-MB-231 (with high LOXL1 and BAG2 expression) with HSP90 inhibitor (IPI-504), HSP70 inhibitor (VER-155008), LOX inhibitor (BAPN), or NAMPT (FK886) inhibitor and doxorubicin, and we observed the survival rate to calculate the drug interactions." (PMID 40426862, 2025). "Importantly, knockdown of BAG2 or pharmacological targeting of HSP90 selectively abrogates the aggregates and renders breast cancer cells hypersensitive to chemotherapeutic drugs." (PMID 36593950, 2023). "Consistently, IHC staining revealed that BAG2 was significantly overexpressed in relapse specimens compared to non-relapse specimens in breast cancer." (PMID 36593950, 2023). "Importantly, silencing of BAG2 or pharmacological targeting of HSP90 substantially reduced the aggregates and increased the sensitivity of chemotherapy in breast cancer." (PMID 36593950, 2023). "In this study, we found that BAG2 could be expressed in CAF and showed that tumors with BAG2+ CAF tend to have reduced DMFS in breast cancer." (PMID 34572878, 2021). "Similar to BAG2, BAG5 is overexpressed in many human tumors (colorectal cancers, lung cancers, breast cancers and skin) with a positive correlation with poor prognosis of breast cancer patients." (PMID 30577483, 2018). "Ninety genes belonging to the GO category of 'apoptosis', including members of the BAG family (BAG1, BAG2, BAG3), as well as members of the breast cancer 'proliferation signatures' (BUB1, PLK1, CCNE1, CCND1 and CCNB1) were also identified as up-regulated in our DTET." (PMID 17014703, 2006). "In addition, we demonstrated a negative prognostic value of BAG2 expression by either CAF or tumor cells for patients with breast cancer, in terms of DMFS." (PMID 34572878, 2021). "Of the 310 breast cancer patients, 10 (3.3%) patients had double positive for BAG2 expression by CAF and tumor cells, 99 (31.9%) had positive, and 201 (64.8%) patients had double negative BAG2 expression." (PMID 34572878, 2021).
gastric cancer (7 papers, 2020 to 2025). A primary or metastatic malignant neoplasm involving the stomach. "Apoptosis has been shown to play an important role in the treatment of gastric cancer, and BCL2-associated athanogene 2(BAG2) has been found to be able to inhibit apoptosis by interacting with multiple apoptosis regulators." (PMID 40755756, 2025). "High expression of BAG2 was significantly associated with T stage and differentiation level of gastric cancer (P < 0.001)." (PMID 32082999, 2020). "It was disclosed that the high expression of BAG2 in gastric cancer is associated with poor prognosis (the cutoff value of FPKM was 4.6, Log-rank P = 0.006)." (PMID 32082999, 2020). "In view of the fact that the high expression of BAG2 associates with poor prognosis in patients with gastric cancer and that is related to several clinicopathological characteristics, we further analyzed the prognosis of high/low expression of BAG2 in different clinicopathological subgroups." (PMID 32082999, 2020). "In summary, our study provides a detailed analysis of the complex roles of BAG2 in gastric cancer, revealing its multiple functions in anti-apoptosis, nucleosome assembly, and maintenance of genome stability." (PMID 40755756, 2025). "The present study offers preliminary evidence suggesting that BAG2 levels are elevated in gastric cancer samples compared to their corresponding normal tissue." (PMID 40755756, 2025). "In summary, the findings underscore the promise of FIIN-2 as a promising therapeutic agent for bag2-driven gastric cancer progression." (PMID 40755756, 2025). "The results of MTT and flow cytometry demonstrated that in WT and gastric cancer cells overexpressing BAG2, HSP70 KO significantly curtailed proliferation and induced apoptosis." (PMID 40755756, 2025). "In summary, the findings underscore the pivotal role of BAG2 in the genesis and progression of gastric cancer." (PMID 40755756, 2025). "In this study, we demonstrate that BAG2 functions as an independent prognostic factor, correlating with unfavorable clinical outcomes in patients with gastric cancer (GC)." (PMID 40755756, 2025). "Despite the initial indications of FIIN-2’s effectiveness in impeding BAG2-CHIP-mediated gastric cancer proliferation in both in vitro and in vivo models, it is acknowledged that the present study is not without its limitations." (PMID 40755756, 2025). "The findings of this study demonstrate that the inhibition of BAG2 significantly suppresses the invasion and migration of gastric cancer cells in Transwell and scratch assays conducted on matrix-coated surfaces." (PMID 40755756, 2025). "BAG2, a molecular chaperone cofactor, plays a substantial role in various cancers, particularly gastric cancer (GC), where it contributes to the anti-apoptotic process." (PMID 40755756, 2025). "Collectively, these findings further substantiate that BAG2 knockdown promotes apoptosis in gastric cancer cells, leading to a substantial reduction in tumor volume and growth rate in vitro and in vivo." (PMID 40755756, 2025). "BAG2 expression has been observed to be elevated in gastric cancer tissues and correlates with the process of gastric carcinogenesis." (PMID 40755756, 2025). "Clinical studies to examine the association of mRNA expression of GREM1, BAG2, OLFM4, TRIP6 and MAGE-A9 and OS in patients with intestinal or diffuse subtype of gastric cancer using different chemotherapeutic agents need to be done." (PMID 34885041, 2021). "BAG2 activates the MAPK pathway and ERK1/2 signaling in oral cancer and gastric cancer, respectively, as seen with BAG2 overexpression." (PMID 34831344, 2021). "In esophageal carcinoma, oral cancer, and gastric cancer, BAG2 overexpression promotes cancer cell proliferation and is associated with poor prognosis." (PMID 34831344, 2021). "Our data confirm that BAG2 can regulate the proliferation of gastric cancer cells by activating AKT/mTOR pathway." (PMID 32082999, 2020).